CCNA2 (cyclin A2)
Diseases named in the same sentence as CCNA2 in open-access papers (continued):
Sharing a sentence is not in itself a finding about the gene and the disease.
tumor (continued). "The genes CCNA2, CKAP2L, NCAPG, and NUSAP1 were not only significantly up-regulated in PCa tissues, but also positively associated with higher Gleason score and tumor stage, implicating significant contributions to the pathogenesis of PCa." (PMID 33927744, 2021). "High expression of CCNB1 and CCNA2 significantly correlates with tumor relapse and predicts poorer prognosis in GC patients (P < 0.05)." (PMID 34126961, 2021). "It is possible that CCNA2–CDK contributes to tumorigenesis by the phosphorylation of oncoproteins and the increased expression level of CCNA2 accelerates cell proliferation once the tumor has formed." (PMID 34737951, 2021). "Conversely, a decreased proliferative capacity of tumor cells has been observed after inhibition of the CDK/CCNA2 complex." (PMID 33718368, 2021). "CCNA2 is a member of cyclin family and participates in modulating cell cycle; knockdown of CCNA2 attenuated the HCC tumor growth, and CCNA2 activation predicted poor prognosis of HCC." (PMID 34491228, 2021). "Our results reveal that CCNA2 is up-regulated in PCa tissues when compared with normal tissues and that its expression is closely connected with Gleason scores, tumor stage in the TCGA database, and GEO data sets." (PMID 33927744, 2021). "Deregulation of cyclin A2 has been reported in a variety of cancers, and is related to chromosomal instability and tumor proliferation." (PMID 34858180, 2021). "As observed in ELF3 knockdown or ANF treatment in vitro experiments in A549 and H1975 cells, cyclin A2, cyclin B1, and cyclin D1 were reduced in xenograft tumor tissues treated with ANF/GEF combination." (PMID 34830169, 2021). "Ccne1, Ccnd1 and Ccna2 were significantly induced in tumours compared to surrounding liver tissues of Ccne1f/f and Cdk2f/f animals." (PMID 34830835, 2021). "Specific cyclin genes such as Ccna2, Ccnb1, Ccnb2, and Ccne1 encoding CYCLIN A2, B1, B2, and E1, respectively, were also upregulated in MMTV-R26Met tumours." (PMID 34646365, 2021). "To further verify the results of bioinformatics analysis, we applied qRT-PCR to validate the mRNA levels of HMMR, SPP1, FN1, CCNB1, CXCL8, MAD2L1 and CCNA2 in 10 paired tumor and adjacent normal tissues with qRT-PCR." (PMID 34126961, 2021). "For instance, (Ma (2019) demonstrated that miR-219-5p inhibited the cell proliferation and cell cycle distribution of ESCC cells by inhibiting the expression of CCNA2, highlighting the role of miR-219-5p and CCNA2 in cell cycle and tumor growth." (PMID 33083112, 2020). "Flow cytometry revealed that tumor cells were arrested in the S phase after down-regulated the expression of CCNA2." (PMID 31956366, 2020). "Among the five hub genes with prognostic values genes, four (CCNA2, DLGAP5, MAD2L1 and KIF2C) were associated with LUSC tumor grade." (PMID 32411535, 2020). "In this study, we used WGCNA analysis to obtain the most relevant gene module for tumor progression, while CCNA2 was the key gene in the group of genes." (PMID 31956366, 2020). "Among the five hub genes, the altered CCNA2, DLGAP5, MAD2L1 and KIF2C were associated with tumor grade, and were significantly up-regulated in LUSC compared with other NSCLC, implicating crucial roles of them in LUSC progression." (PMID 32411535, 2020). "The data from TCGA showed that the average expression level of CCNA2 in tumor tissues was 1.87, and the value in adjacent tissues was 0.69." (PMID 31956366, 2020). "These two genes’ (TGFB2 and CCNA2) relationship with platelets and immunity has been reported by many tumor-related studies." (PMID 33195410, 2020). "Aberrant expression of CCNA2 has been detected in a variety of cancers, and deregulation of CCNA2 was closely related to tumour proliferation and chromosomal instability." (PMID 32951327, 2020). "Some studies have confirmed that CCNA2 has oncogene activity, and its high expression or overexpression is closely related to the malignant transformation of tumor cells." (PMID 30995921, 2019).
tumor (continued). "Our real-time PCR results reveal that CCNA2 expression was significantly upregulated in ESCC tissues compared with the adjacent non-tumor tissues (p < 0.001)." (PMID 30766610, 2019). "In conclusion, the up-regulation of BUB1B, CCNA2, CDC20, CDK1, and WEE1 in tumor tissues are associated with worse OS and DFS in PDAC and is correlated with advanced tumor stage and tumor development." (PMID 30765611, 2019). "In previous studies, it is reported that overexpression of CCNA2 is involved in tumor transformation and progression in numerous types of cancer." (PMID 31001122, 2019). "This study provides novel evidence that ESRP1 can induce tumor cell G1-phase cell cycle arrest by regulating cyclin A2 mRNA stability." (PMID 31362365, 2019). "Here, Cyclin A2 (R ≈ 22) was found to be the highest up-regulated gene in tumor samples, while c-Fos (R ≈ 0.1) was the most down-regulated gene." (PMID 31023373, 2019). "CCNA2 gained our attention because it is a well-known regulator in cell cycle progression and reported to be involved in tumor progression." (PMID 30766610, 2019). "Our results not only highlight the molecular mechanisms of ESRP1 in the context of tumor cell proliferation, but further provide new insights with respect cyclin A2 post-transcriptional regulation." (PMID 31362365, 2019). "In this research, we further assessed the differential expression of five hub genes (TPX2, KIF2C, CDCA8, BUB1B, and CCNA2) in various clinical stages, and the results showed that their expression was significantly increased in advanced tumour stages." (PMID 31285741, 2019). "Twenty-nine (45.3%) tumours were classified as high proliferative tumours assessed by Ki-67 protein expression and correlated with tumours with high expression of cyclin A2 (Rho = 0.30; p = 0.016) and cyclin B1 (Rho = 0.37; p = 0.003)." (PMID 29785357, 2018). "In multivariate analysis for an overall five-year survival (OS), we found an adverse independent prognostic value for cyclin A2 high expression (p = 0.031) and for advanced tumour stage (p < 0.001)." (PMID 29785357, 2018). "We identify new mechanisms of cyclin A2/E1 activation, and we explore the clinical and molecular characteristics of this tumor subgroup." (PMID 30531861, 2018). "High expression values were also noted for cyclin A2, observed in more than 80% of tumour cells, and lower frequencies were observed for cyclins B1 and E1." (PMID 29785357, 2018). "This can assist oncologists in the planning treatment options for each patient with OSCC, indicating better and more adjusted chemotherapy or radiotherapy protocols considering the cyclin A2 status of the tumours." (PMID 29785357, 2018). "Our results suggest that tumours with cyclin A2 expression will drive the cells to division thus rendering them some growth potential." (PMID 29785357, 2018). "With provided TF-TG correlation coefficient, users get TF list targeting CCNA1, CCNA2 and see that the correlation coefficients are different between normal samples and selected tumor samples." (PMID 29504910, 2018). "Our data indicate that for South European populations, cyclin A2 is a major prognostic marker, being an indicator of high proliferative status tumours but importantly also of a poor patient's survival with these tumours." (PMID 29785357, 2018). "High Ki-67 expression was observed in tumours with high expression of cyclin A2 (Rho = 0.30; p = 0.016) and cyclin B1 (Rho = 0.37; p = 0.003)." (PMID 29785357, 2018). "Cyclin A2 expression was observed in 54 (83.1%) tumours, cyclin D1 in 58 (89.2%), cyclin B1 in 39 (60%), and cyclin E in 21 (32.8%)." (PMID 29785357, 2018).
tumor (continued). "In multivariate analysis for OS, we only found an independent prognostic value for stage and cyclin A2 expression, where tumours with advanced stage (p < 0.001) and with high expression of cyclin A2 (p = 0.031) had lower OS." (PMID 29785357, 2018). "HBV potentially induces HCC directly via HBx protein that has a potential exon of retinoic acid receptor B and cyclin-A2 gene integrated to host DNA (usually regulator proto-oncogene and tumor suppressor genes)." (PMID 28837651, 2017). "Collectively, WA inhibited tumor masses in vivo in a subcutaneous xenograft mouse model of HCC, the underlying insights of which were related to the miR-22-repressed CCNA2 pathway." (PMID 27738335, 2016). "The area under the curve (AUC) of FXR (AUC = 87.5%), miR-22 (AUC = 91.4%), and CCNA2 (AUC = 98%) exhibited good sensitivity for tumor prediction." (PMID 27738335, 2016). "Other targets, such as CCNA2, involved in repressing the expression of cyclin E and tumor cell proliferation." (PMID 27143508, 2016). "For assessment of Sphase arrest in the tumor cells, cyclin A2 expression was analysed byimmunohistochemical method." (PMID 26189912, 2015). "The expression levels of cyclin A2 in the tumor samples studied by immunohistochemistry were in line with the results obtained by WB, with decreased cyclin A2 levels in GFP-GATA3-S308A tumors." (PMID 25479686, 2014). "The results showed that HCPT treatment (30 mg/kg) significantly increased cyclin A2 protein levels and significantly decreased p27 protein levels in tumor tissue." (PMID 23301056, 2013). "Cyclin A/Cdk2 (CCNA2) and CCNB1 are present in many tumours and some were previously associated with poor prognosis and in metastasis." (PMID 19753302, 2009). "Among the significant genes that show a high expression in tumours with unfavourable outcome, cell cycle associated genes can be found (E2F1, CCNA2, CCNB1, KIFC1)." (PMID 17531100, 2007). "CCNA2 has been proved as a potential target for tumor immunotherapy and high-avidity CCNA2-specific cytotoxic T lymphocyte could be generated using CD40-B cells as antigen-presenting cells." (PMID 40345591, 2025). "In our study, the knockdown of CCNA2 induced the apoptosis of tumor xenografts in nude mice." (PMID 40345591, 2025). "Thus, we discovered the moonlighting function of 6PGD in promoting tumor growth and migration via CCNA2 and HMGA2, respectively." (PMID 40611205, 2025). "This confirms that prolonged CDK2 inhibition in vivo can exert sustained control of CCNE1-amplified tumors, and that rebound compensation by CDK4/6 is not present to a level sufficient to significantly restore Rb phosphorylation, cyclin A2 expression, or tumor growth." (PMID 38047585, 2024). "Additionally, CCNA2 has been shown to foster abnormal tumor cell proliferation and epithelial-mesenchymal transition in NSCLC." (PMID 39669580, 2024). "Furthermore, cell cycle genes such as CDK5, CCNA2, CCNB1, and CCNB2, associated with tumor relapse and metastasis, are more highly expressed in DAB2IP-low Luminal A tumors." (PMID 39418101, 2024). "Thus far, Cyclin A2 (CCNA2) has emerged as a multifaceted player in CRC tumor biology, influencing cell-cycle progression, oncogenesis, cell proliferation, and apoptosis." (PMID 38167453, 2024). "In particular, CCNA2, CCNB2, CDK1, and TOP2A were found to be significantly upregulated in HBV‐positive HCC tumor samples and may serve as promising diagnostic biomarkers." (PMID 38895552, 2024). "The ‘tumor cells 1’ cluster had the gene expression characteristic of stem-like tumor cells with an elevated expression of genes involved in cell division and chromosome segregation such as Top2a, Mki67, Cenpf, Cenpe, Incenp, Anln, Ccna2, Kif20b, Ccnb1, and Smc4." (PMID 39769061, 2024). "Finally, we detected a sustained decrease in cell proliferation in KPF/FC tumours (as measured by IHC for cyclin A2) beginning 4 h after treatment with RMC-7977, with maximal inhibition maintained at 12 and 24 h and a partial recovery at 48 h." (PMID 38588697, 2024).
tumor (continued). "CCNA2, a cyclin family member, has a crucial function in the cell cycle and tumor development." (PMID 38895552, 2024). "Out of the 55 upregulated genes, a 5 gene-signature (CDK1, EZH2, CCNB1, CCNA2, and AURKA) involved in cell regeneration was positively correlated with the status of tumor hypoxia and clustered with stemness-associated genes, as recognized by Parametric Gene Set Enrichment Analysis (PGSEA)." (PMID 37189841, 2023). "The insertion of HBV DNA into the CCNA2 and CCNE1 genes, which are associated with the G1/S transition of the cell cycle, disrupts the biological process and promotes tumor development; KMT2B is a tumor suppressor gene that prevents the uncontrolled growth and division of cells." (PMID 36992198, 2023). "Moreover, CCNA2’s role in metastasis means that its upregulation will increase cell migration of tumour cells and thus increase the likelihood of secondary tumour formation." (PMID 36937454, 2023). "Following that, the top 100 correlated proteins with CEP55 were collected from the GEPIA2 database, where the proteins KIF11, MK167, CDK1, PLK1, and CCNA2 represented the top 5 proteins correlated with CEP55 in the tumor microenvironment that influence immune cells in TME." (PMID 37175004, 2023). "CCNA2 is involved in the proliferation, invasion, and differentiation of normal and tumor cells." (PMID 37476415, 2023). "To explore the biological function of CCNA2 in different cancer types, we firstly utilized the GSVA to calculate the enrichment scores of 50 canonical tumor associated pathways in pancancer level; then, the correlation of those enrichment scores and CCNA2 expression was estimated." (PMID 35401923, 2022). "Whether CCNA2 involves in the tumor microenvironment and pathogenesis of different tumors through common or specific mechanisms remains unclear." (PMID 35401923, 2022). "Specifically, the inhibition of DBF4, CCNA2, CCNB1, MCM6, CDC45, CHEK1, and CDC6 may be implicated in KCNQ1-mediated tumor suppression." (PMID 35216393, 2022). "All those results indicated that CCNA2 could regulate immune cell infiltration via different mechanism under various tumor microenvironments, and further experiment needs to decipher the heterogeneous mechanisms." (PMID 35401923, 2022). "It was found in our study that CCNA2 was involved in tumor proliferation, invasion, and differentiation, thus could be treated as a novel and promising diagnostic also therapeutic targets for cancers." (PMID 35401923, 2022). "In summary, our study shows that CDCA7, a copy number amplification gene in ESCC, may act as a tumor promoter via regulating CCNA2 directly and accelerate the cell cycle process of ESCC cells." (PMID 34737951, 2021). "The distribution of BUB1B and CCNA2 expression correlated with tumor stage." (PMID 34253236, 2021). "Interestingly, Ccne1-depleted tumours also displayed reduced levels of Ccnd1 and Ccna2 compared to WT mice." (PMID 34830835, 2021). "The expression of CCNA2 and CKAP2L showed positive association with infiltrating levels of B cells, CD8+ T cells, CD4+ T cells, neutrophils, macrophages, and dendritic cells, but were weakly positive with tumor purity." (PMID 33927744, 2021). "Our results reveal a novel mechanism of CDCA7 that it may act as an oncogene by directly upregulating CCNA2 to facilitate tumor progression in ESCC." (PMID 34737951, 2021). "Flow cytometry experiments indicated that after the down-regulation of CCNA2, tumor cells were enriched in the S phase, suggesting that lowering CCNA2 may affect cell cycle transformation." (PMID 31956366, 2020). "CCNA2, DLGAP5, MAD2L1, and KIF2C were significantly up-regulated compared to other subtypes, and associated with tumor stage in LUSC, suggesting that they might tightly be involved in progression and prognosis of LUSC." (PMID 32411535, 2020).
tumor (continued). "CCNA2 participates in the modulation of RhoA activity and its dysregulation by autophagy in the late phase of mitosis appears to be associated with EMT, affecting the aggressiveness of the tumor." (PMID 33665162, 2020). "In summary, CCNA2 is at the core of tumor development and progression, and many factors might affect the progression of the tumor by affecting the expression of CCNA2." (PMID 31956366, 2020). "At present, only RRM2, CDK1 and CCNA2 were identified as tumor therapeutic targets." (PMID 33083112, 2020). "Inhibition of CCNA2 complexes also has been shown to impair the proliferation of tumour cell lines." (PMID 32951327, 2020). "LINC00968 has been studied mainly in cancer pathogenesis; it may promote tumor cell growth, migration, and invasion upon activation of Wnt/β-catenin or by targeting cyclin-A2." (PMID 31547203, 2019). "Moreover, overexpression of BUB1B, CCNA2, CDC20, and CDK1 in tumor tissues was significantly associated with disease-free survival (DFS) in PDAC patients (Log rank P=0.00565, P=0.0357, P=0.00104, and P=0.00121, respectively)." (PMID 30765611, 2019). "Our results demonstrate that miR-219-5p might function as a tumor suppressor by directly targeting CCNA2 expression." (PMID 30766610, 2019). "In addition, many studies have reported that hsa-miR-30a-5p is a tumor suppressor in GC, and recent studies have shown that CCNA2, MYBL2, DTL, and STMN1 are regulated by hsa-miR-30a-5p." (PMID 29912172, 2018). "Importantly, we found an independent prognostic value for cyclin A2 protein in OSCC indicating a poor overall survival for patients with tumours with high expression of cyclin A2." (PMID 29785357, 2018). "Upregulation of LEFTY may serve as a useful clinical marker for the therapeutic effects of progesterone for Em Cas, leading to inhibition of tumor cell proliferation through alteration in Smad2-dependent transcription of cyclin A2." (PMID 29268772, 2017). "Most of the validated mRNAs provided unique information about tumor aggressiveness, however, three pairs of transcripts in the validated set of 23 were correlated (P‐values < 0.05): CCNA2 and TPX2 (r2 = 0.61); SRD5A2 and DPT (r2 = 0.56); and SRD5A2 and FBLN1 (r2 = 0.73)." (PMID 28145099, 2017). "To identify the underlying mechanism of WA in HCC cell proliferation, we therefore analyzed the relative expressions of FXR, miR-22, and CCNA2 in both tumor and adjacent normal tissues derived from HCC patients (data downloaded from GEO database in NCBI, GSE22058)." (PMID 27738335, 2016). "Moreover, we demonstrated that CCNA2 is down-regulated in MCF-7 tumor xenografts treated with tamoxifen compared with control in vivo." (PMID 24622579, 2014). "Downregulation of cyclin A2 (Ccna2), Polo-like kinase 1 (Plk1) and the centromer protein A (Cenpa) which are typically upregulated in tumour cells to foster cell cycle and mitosis agree well with the observed cell cycle arrest and demonstrate the therapeutic effect of these experimental inhibitors." (PMID 21152443, 2010). "This subclass was characterised by under-expression of cell-cycle or proliferation-associated genes such as CCNA2 and CCNB2. these features could explain the less aggressive behaviour of these tumours." (PMID 19826428, 2009). "Dysregulation of CCNA2 may result in uncontrolled cell proliferation and promote tumor formation." (PMID 38895552, 2024). "In addition, CDK1, CDC20, CCNA2, CCNB1 and CCNB2 expressions may be involved in the regulation of monocytes and tumor-associated macrophages (TAMs) in HCC, respectively." (PMID 36605491, 2023). "It has been suggested that these adipocyte derived EVs might promote tumor growth through inducing cell proliferation by decreasing the level of the anti-tumor miRNA-34a and upregulating the pro-cancer ubiquitin-specific peptidase 7/Cyclin A2 signaling pathway (USP7/CCN2A)." (PMID 37240762, 2023). "CCNA2 could also act as a significant downstream facilitating tumor progression." (PMID 35401923, 2022).